MDM2 (MDM2 proto-oncogene)
Diseases named in the same sentence as MDM2 in open-access papers (continued):
Sharing a sentence is not in itself a finding about the gene and the disease.
cancer (continued). "Aberrant splice variants of the MDM2 and MDMX genes have been identified from various aggressive forms of cancers." (PMID 32075226, 2020). "MDM2/4 as well as EGFR amplifications, have recently been described in association with hyperprogression on ICI in diverse cancers." (PMID 32110946, 2020). "Southern blot and PCR methods have identified more frequent MDM2 gene amplification in metastatic or recurrent osteosarcomas than the corresponding primary cancer." (PMID 32477121, 2020). "Supporting this notion, the ability of mutant RBM10 to bind to MDM2 is reduced as measured by co-IP-IB analysis in cancer cells." (PMID 32947864, 2020). "It is notable that MDM2 is overexpressed in approximately 10% of cancers and the fact that it can either have a growth promoting, or suppressive activity, depending on cellular conditions, sheds new light on its role in cancer development." (PMID 32453417, 2020). "Treatment with DIM decreased MDM2 at messenger RNA (mRNA) and protein levels, inhibited cancer cell proliferation, and induced cell cycle arrest and apoptosis." (PMID 32629830, 2020). "To date, there are also some specific RING E3 inhibitors (e.g., IAP and MDM2) that have entered clinical research and provide a promising strategy for cancer chemotherapy and prevention." (PMID 32905356, 2020). "Our results also show synergistic anti-cancer activity when DIM is combined with cis-imidazoline MDM2 inhibitors, a potential therapeutic strategy for CRC." (PMID 32629830, 2020). "Chou et al25 proposed that AMPK can reverse the mesenchymal phenotype of cancer cells by targeting the Akt‐MDM2‐Foxo3a signaling axis, while Saxena et al26 hold that high level of AMPK was an accelerator of pathological EMT." (PMID 32519437, 2020). "The current results propose a new role for the MDM2/MDMX inhibitor as a potential strategy to treat cancer." (PMID 31892970, 2020).
cancer (continued). "Further biological and biochemical studies demonstrate that MDM2 is involved in cancer cell growth, apoptosis, cancer cell evasion, metastasis, and resistance to chemotherapy." (PMID 32397368, 2020). "Many spliced isoforms of MDM2 are observed in humans with cancer, and the cDNA coding some of these spliced isoforms is also capable of transforming cells." (PMID 32854179, 2020). "We, and others, have been interested in developing various classes of MDM2 inhibitors for cancer therapy and other diseases, including antisense oligonucleotides, natural products, and synthetic small molecule compounds." (PMID 32397368, 2020). "Our lab has a long history of developing novel strategies to target MDM2 for cancer therapy and prevention." (PMID 33291373, 2020). "Murine double minute 2 (MDM2 ((HDM2in human)) is a multifunctional intrinsically disordered protein that is amplified in approximately 10% of cancers including sarcomas, lymphomas, and B-cell lymphocytic leukemia." (PMID 32453417, 2020). "Elsewhere, a study found that advanced cancer patients with MDM2 overexpression developed HPD after treatment with PD-1 inhibitor." (PMID 33195412, 2020). "The MYC- and MYCN-transformed cone precursors’ sensitivity to MDM2 knockdown suggests that MDM2 upregulation is an important part of MYC- as well as MYCN-mediated cancer initiation." (PMID 33425720, 2020). "The oncoprotein mouse double minute 2 (MDM2) promotes cell survival, proliferation, invasion, and therapeutic resistance in many types of cancer." (PMID 32477121, 2020). "These include well-known cancer-associated genes, such as CCND1 (25 tumors), CDK4 (25 tumors), MDM2 (23 tumors), SETDB1 (23 tumors), ERBB3 (11 tumors), ERBB2 (11 tumors), MYC (10 tumors) and MYCN (five tumors)." (PMID 32025003, 2020). "In recent years, a growing amount of evidence supports the involvement of Mdm2 overexpression in the induction of cancer EMT." (PMID 33114139, 2020).
cancer (continued). "When combined with imidazoline MDM2 inhibitors (Nutlin-3a and Idasanutlin/RG-7388), synergism was observed in cancer cell growth inhibition." (PMID 32629830, 2020). "Targeting MDM2 by gene-silencing or pharmacological blockade with AMG-232 enhanced T-cell killing of cancer cells." (PMID 32655895, 2020). "The anti-cancer drugs, doxorubicin and VP-16 act inside cancer cells by successfully disrupting the MDM2-DAXX-HAUSP complex and degrading MDM2 expression." (PMID 32489456, 2020). "Paradoxically, Slug (SNAI2), which belongs to Snail transcriptional repressor family, can be downregulated by MDM2 to enhance E-cadherin expression and repress cancer invasiveness." (PMID 32477121, 2020). "MDM2 rs3730485 and MDM4 rs4245739 variants were studied in different types of cancer, together or in combination with one or with the other two mentioned variants, but from our knowledge, AML patients were not investigated." (PMID 32492903, 2020). "Increased MDM2 expression is commonly observed in different types of cancers, indicating its oncogenic function." (PMID 32477121, 2020). "We also explain various strategies that can be used to inhibit the NFAT1-MDM2 pathway in cancer cells, and also discuss the dual inhibitors of NFAT and MDM2 with potent in vitro and in vivo anticancer activity." (PMID 32397368, 2020). "One approach for breast cancer therapy is through inhibition of mouse double minute 2 (MDM2) oncoprotein that is overexpressed in these cancer cells." (PMID 32967170, 2020). "Accordingly, the overexpression of MDM2 has been observed in many cancer types, and thus it has been attracted as a drug target for cancer therapy." (PMID 32882786, 2020).
cancer (continued). "Mdm2 and MdmX RING domains have been identified as the functional domain in several aberrant splice variants of Mdm2 and MdmX identified from cancers, such as HDM2ALT1 and HDMX211." (PMID 32075226, 2020). "These intrinsic characteristics make MDM2 a hopeful anti-cancer target and a molecular-based cancer biomarker." (PMID 32667627, 2020). "If proven correct using in vivo cancer models or human specimens, the proposed mechanism would imply that TSG101 levels should be generally lower in cancers that overexpress MDM2 or lack p19Arf." (PMID 32075127, 2020). "MDM2 overexpression was also found in head and neck squamous carcinomas, indicating its contribution in cancer development." (PMID 32477121, 2020). "Many of the pathway level shifts we observed suggest that MDM2 plays a role in a wide variety of cancer-related metabolic processes, including ceramide metabolism, amino acid synthesis, lipogenesis, and inflammation." (PMID 32759684, 2020). "We detect known cancer drivers in these putative double minutes, including MDM2 (four samples) and CDK4 (four samples)." (PMID 32025003, 2020). "Aberrant MDM2 protein expression is documented in a wide variety of human cancers and is thought to be due to gene amplification as well as transcriptional and post-translational regulation 24-26." (PMID 33061808, 2020). "For example, cancer patients with overexpression of MDM2 developed HPD after PD-1 inhibitor treatment." (PMID 33195412, 2020). "Alternative splice forms of MDM2 have been found in various human cancers, indicating diversified regulatory mode of MDM2 and its transcriptional variants." (PMID 32477121, 2020).
cancer (continued). "Understanding the mode of action of this class of MDM2 targeted drugs will be important as patients with diverse cancer types begin to be treated with MDM2 inhibitors." (PMID 32874188, 2020). "Amplified MDM2 has been reported in human sarcomas and in 10% of various human cancers including gastric carcinomas." (PMID 31759358, 2019). "Recently, we reported a novel function for FKBP12 in oncoprotein mouse double minute 2 (MDM2) self-ubiquitination and degradation, which greatly enhanced the sensitivity of cancer cells to chemotherapy." (PMID 31428819, 2019). "Mdm2 often has increased expression levels in a variety of human cancers and promotes cancer cell proliferation." (PMID 30627419, 2019). "It acts as an important defense protein against cancer onset and evolution and is negatively regulated by interaction with the oncoprotein MDM2 (murine double minute 2)." (PMID 30875980, 2019). "Amplification of the oncogenes ERBB2, CDK6, MDM2 affected dependency, as did point mutations in PIK3CA, KRAS, NRAS, VHL and BRAF, validating our approach to highlight genes with significance in cancer." (PMID 30803482, 2019). "In recent decades, much attention has been paid to discover potential inhibitors against MDM2 in order to cure cancer." (PMID 31906032, 2019). "Since cardiovascular side effects of anti-cancer therapies are a recurrent problem, characterizing the cardiovascular function of MDM2 has become a pressing issue." (PMID 31921839, 2019). "Regardless, the frequency with which aberrant MDM2/MDMX expression is seen in cancer points towards a definitive role for MDM2 and MDMX in tumorigenesis." (PMID 31905981, 2019). "MDM2 levels are elevated in a variety of cancers and this elevation has been attributed in some cases to an increase in translation of the pool of MDM2 transcripts, based on increased transcription from the P2." (PMID 30723103, 2019).